ENSG00000288646 (novel protein)
Synonyms: LOC128031835
Gene: Protein-coding gene on chromosome 6 (53,065,602 to 53,065,673, forward strand). Ensembl gene ENSG00000288646.
Homologues: Orthologues: mouse Gm64583 (100% identical).